GCG (glucagon)
Diseases named in the same sentence as GCG in open-access papers (continued):
Sharing a sentence is not in itself a finding about the gene and the disease.
renal cell carcinoma (4 papers, 2022 to 2025). "These metabolites are involved in key metabolic pathways, including glucagon signaling, the TCA cycle, pyruvate metabolism, and renal cell carcinoma pathways in AMI patients." (PMID 40822584, 2025). "These metabolites are involved in key pathways such as glucagon signaling, the TCA cycle, pyruvate metabolism, and renal cell carcinoma pathways, indicating disruptions in energy metabolism, glucose regulation, and oxidative stress." (PMID 40822584, 2025). "Moreover, our findings demonstrated the dysregulations of Glucagon signaling, TCA cycle, Pyruvate metabolism, Renal cell carcinoma, and Lysine degradation pathways in AMI." (PMID 40822584, 2025).
alcoholic fatty liver disease (3 papers, 2023). Lipid infiltration of the hepatic parenchymal cells that is due to alcohol abuse. "In a cross-sectional study of 172 participants with T2DM, the relationship between the glucagon to insulin ratio and the presence of non-alcoholic fatty liver disease was examined." (PMID 37762748, 2023). "The GCG receptor agonists have been shown to counteract hepatocarcinogenesis through the cAMP-PKA-EGFR-STAT3 axis in a non-alcoholic mouse model, while GCG may promote hepatocarcinogenesis in patients suffering from non-alcoholic fatty liver disease." (PMID 38143739, 2023).
amyloid (3 papers, 2013 to 2023). "It turns out that another substrate for neprilysins (next to glucagon, insulin, substance P and many others) is amyloid, thus, lowering its level promotes the formation of its deposits and the formation of amyloid plaques." (PMID 32366041, 2020).
brain injury (3 papers, 2020 to 2026). Acute and chronic (see also brain INJURIES, CHRONIC) injuries to the brain, including the cerebral hemispheres, CEREBELLUM, and brain STEM. "In a rodent model of ischemic brain injury, insulin and glucagon improved poststroke outcome in animal models by decreasing glutamate in the circulation and cerebrospinal fluid." (PMID 33510613, 2020). "In addition, the glucagon signaling pathway is also enriched in the metabolome, and it has been reported that glucagon-like peptide-1 (GLP-1) can reduce neuroinflammation induced by brain injury and play a neuroprotective role." (PMID 36507346, 2022).
carcinoid syndrome (3 papers, 2021 to 2022). "Twenty-three (54.8%) cases were functional tumors, including carcinoid syndrome, but there were also rare ones secreting glucagon, growth hormone-releasing hormone (GHRH), and PTH-related protein (PTHrP)." (PMID 35207193, 2022).
carcinoids (3 papers, 1988 to 2022). "Interestingly, peptides typical of the neuroendocrine differentiation of pancreatic tumors such as glucagon and pancreatic polypeptide were expressed in 80% and 100% of the strumal carcinoids tested." (PMID 35528006, 2022). "The presence of a number of regulatory peptides (bombesin, gastrin, glucagon, somatostatin, calcitonin and ACTH) was compared in 30 typical carcinoid tumours and 27 well differentiated neuroendocrine carcinomas (atypical carcinoids) using conventional immunocytochemistry." (PMID 2906252, 1988).
dependence (3 papers, 2001 to 2024). "The 24-hour urinary CPR <20 μg/day, fasting CPR <0.48 ng/m, and ΔCPR <1.0 ng/mL in glucagon test have been used as indices of insulin dependence." (PMID 35574023, 2022).
diabetes insipidus (3 papers, 2010 to 2024). A disorder characterized by excretion of large amounts of urine, accompanied by excessive thirst. "Our data clearly show that copeptin response following glucagon stimulation rests on an intact posterior pituitary function and is lost in patients with partial or overt diabetes insipidus." (PMID 26578365, 2016).
diabetic neuropathy (3 papers, 2023 to 2025). A chronic, pathological complication associated with diabetes mellitus, where nerve damages are incurred due to diabetic microvascular injury involving small blood vessels that supply these nerves, resulting in peripheral and/or autonomic nerve dysfunction. "Of note, adiponectin can influence insulin, glucagon, glucose metabolism, TGs and free-fatty acids concentrations, while PPARγ can change accordingly to medium chain ACCs, being involved in antioxidant activity as well as in peripheral nerve injury and diabetic neuropathy." (PMID 37817933, 2023).
Down syndrome (3 papers, 2015 to 2025). "Co-labelling with antibodies against smooth muscle actin to mark the spleen vasculature, and insulin and glucagon to identify pancreatic islets, showed no overall disruptions in tissue morphology in the Down syndrome samples." (PMID 26658127, 2015).
dumping syndrome (3 papers, 2020 to 2022). A disorder of the gastrointestinal tract. "Plasma glucagon was also measured in this study; baseline glucagon concentrations were similar between controls and subjects with dumping syndrome, and the glucagon levels peaked and remained elevated after 20 minutes in subjects with dumping syndrome." (PMID 35399928, 2022).
endometriosis (3 papers, 2022 to 2026). The growth of functional endometrial tissue in anatomic sites outside the uterine body. "We found a significant increase in CD10 expression in endometriosis, which possibly explains the decrease in glucagon, GLP-1, visfatin, and ghrelin." (PMID 36142272, 2022).
epilepsy (3 papers, 2024 to 2025). A brain disorder characterized by episodes of abnormally increased neuronal discharge resulting in transient episodes of sensory or motor neurological dysfunction, or psychic dysfunction. "In cases where epilepsy or other contraindications preclude the ITT, a glucagon stimulation test (GST) is an alternative." (PMID 39415786, 2024).
fibrosis (3 papers, 2023 to 2024). the formation of excess fibrous connective tissue in an organ or tissue in a reparative or reactive process. "However, it is counterintuitive in that normal liver never develops spontaneous fibrosis even in a prolonged fasting condition with high blood glucagon concentration." (PMID 38233853, 2024).
gastric cancer (3 papers, 2021 to 2026). A primary or metastatic malignant neoplasm involving the stomach. "By analyzing the gastric cancer samples and paired adjacent normal tissues in TCGA, we found that these 27 paired samples exhibited different GCG expression patterns, which in turn reflected the high heterogeneity of GC." (PMID 35898512, 2022). "Second, while SERPINE1 was functionally characterized, the roles of other signature components (e.g., C6, GRP, GCG) in gastric cancer remain unclear and merit further investigation." (PMID 41551463, 2026).
glucosuria (3 papers, 2019 to 2025). "However, glucosuria increases the risk of genitourinary tract infection and dehydration, and glucagon secretion may lead to an overproduction of ketone bodies." (PMID 39925851, 2025). "The glucosuria results in lower serum glucose values which decreases insulin release and increases glucagon release from the pancreas." (PMID 31488052, 2019). "Because changes in plasma glucagon and insulin concentrations cannot explain the increase in EGP, we hypothesised that a renal neuronal signal is generated in response to glucosuria and leads to the stimulation of hepatic glucose production." (PMID 32827269, 2020).
Hepatic failure (3 papers, 2013 to 2025). "Hepatic failure is associated with increased pancreatic glucagon levels (true hyperglucagonaemia suppressed by glucose)." (PMID 24137355, 2013). "Hepatic failure is associated with increased pancreatic glucagon levels (true hyperglucagonaemia is suppressed by glucose)." (PMID 24137355, 2013).
hyperthyroidism (3 papers, 2011 to 2021). Overactivity of the thyroid gland resulting in overproduction of thyroid hormone and increased metabolic rate. "With regards to glucagon, its secretion and metabolic clearance rates have been reported increased, explaining the normal fasting plasma levels described in hyperthyroidism." (PMID 21941681, 2011). "In addition, abnormal glucagon secretion, hyperthyroidism, higher serum thyrotropin, more severe dawn phenomenon and acute stress conditions could prompt glycemic variability." (PMID 34556157, 2021).
hypopituitarism (3 papers, 2016 to 2024). A condition of diminution or cessation of secretion of one or more hormones from the anterior pituitary gland. "In the absence of multiple pituitary hormone deficiencies in neonates, an inappropriately large glycemic response to glucagon stimulation may be considered diagnostic, particularly when plasma insulin concentration is low." (PMID 37454648, 2024). "Copeptin concentrations significantly increased over baseline 150 and 180 min following glucagon stimulation in controls and patients with intact pituitary function but not in hypopituitarism." (PMID 26578365, 2016).
insomnia (3 papers, 2022 to 2024). A sleep disorder characterized by difficulty in falling asleep and/or remaining asleep. "Pain can induce the secretion and release of various hormones, including catecholamines, glucagon, and antidiuretic hormone, via central and sympathetic nerves, leading to increased brain excitability and causing insomnia." (PMID 37142982, 2023).
ischemia (3 papers, 2019 to 2025). A hypoperfusion of the BLOOD through an organ or tissue caused by a PATHOLOGIC CONSTRICTION or obstruction of its BLOOD VESSELS, or an absence of BLOOD CIRCULATION. "Co-administration of exenatide and glucagon elicited better recovery of the contractile function after ischemia in the isolated hearts." (PMID 38675485, 2024).
lipid metabolism disorders (3 papers, 2019 to 2025). "These factors include lipid metabolism disorders, weakened incretin effect, elevated basal glucagon levels, increased renal glucose reabsorption, and neurotransmitter dysfunction in the brain." (PMID 40386230, 2025).
liver cancer (3 papers, 2019 to 2023). An epithelial or non-epithelial malignant neoplasm that arises from the liver. "To provide a rationale for targeting glucose metabolism in liver cancer via glucagon-stimulated gluconeogenesis, we probed the necessity of glucose for cell viability." (PMID 35123542, 2022). "We therefore proposed the following question: can glucagon signaling induce gluconeogenic gene expression to perturb liver cancer?" (PMID 35123542, 2022). "For the first time, we report a potential tumor suppressive role for glucagon/GCGR in liver cancer." (PMID 35123542, 2022). "Here, we test the hypothesis of whether glucagon signaling can activate gluconeogenesis to reduce tumor proliferation in models of liver cancer." (PMID 35123542, 2022). "Concordantly, we hypothesize that liver cancer cells themselves would be largely unaffected by circulating glucagon directly." (PMID 35123542, 2022). "In addition, glucagon-induced acetylation of different energy-sensing factors is involved in the advancement of nonalcoholic fatty liver disease (NAFLD) to liver cancer." (PMID 30995792, 2019). "However, it is unclear whether glucagon signaling is critical in liver cancer cells or whether full activation of gluconeogenesis could antagonize pro-tumorigenic glycolysis." (PMID 35123542, 2022). "Since gluconeogenesis biochemically opposes glucose catabolism, we hypothesized that glucagon signaling would have a tumor suppressive effect in liver cancer cells that are responsive to glucagon, especially if they express sufficient levels of GCGR and key gluconeogenic enzymes." (PMID 35123542, 2022). "We next examined a recent patient-derived xenograft cell line, M7571, to determine whether a more patient-proximal liver cancer model was amenable to restoration of gluconeogenic gene expression after treatment with glucagon and our panel of epigenetic inhibitors." (PMID 35123542, 2022). "In summary, these findings may reveal that glucagon-induced acetylation of different energy-sensing factors has diverse effects on tumorigenesis and hepatocarcinogenesis, and also provides potential strategies for the treatment of liver cancer." (PMID 30995792, 2019). "Collectively, our data indicate that glucagon cannot induce a uniform augmentation in gluconeogenic gene expression in liver cancer cell lines and that SNU398 cells are most responsive to glucagon upon GCGR overexpression, in terms of downstream signaling." (PMID 35123542, 2022). "However, whereas our findings support the anti-tumorigenic role of glucagon and GCGR in one model of liver cancer, we were unable to detect increases in gluconeogenic gene expression." (PMID 35123542, 2022). "We tested this phenotype in numerous other liver cancer cell lines for glucagon/GCGR robustness but did not measure equivalent changes in cell number compared to SNU398 at 100 nM glucagon." (PMID 35123542, 2022). "Of note, we did not observe a decrease in GCGR expression with glucagon treatment in SNU398 or other liver cancer cell lines, but rather a consistent increase." (PMID 35123542, 2022). "In diabetic patients with liver cancer, we believe it important to study the potential cell non-autonomous effects of normal, glucagon-responsive hepatocytes as to their ability to facilitate tumor cell growth by releasing glucose into the tumor microenvironment." (PMID 35123542, 2022). "Therefore, future studies on glucagon signaling in liver cancer could analyze metabolomics profiling of SNU398 GCGR cells with or without glucagon, compared to a cell line that is unresponsive, regardless of glucagon treatment." (PMID 35123542, 2022).
Liver dysfunction (3 papers, 2022 to 2024). "Liver dysfunction in NAFLD patients has been linked to hypersecretion of glucagon independently of a change in glucose tolerance and is instead being attributed to a disruption of the liver-a-cell axis." (PMID 36456963, 2022). "A glucagon stimulation test was also not conducted but may be of use when there is diagnostic uncertainty, as a markedly inadequate response raises the likelihood of impaired gluconeogenesis due to liver dysfunction." (PMID 39372824, 2024).
mucositis (3 papers, 2018 to 2024). Mucositis is inflammation and damage of the mucous membranes lining the mouth and other parts of the gastrointestinal (GI) tract. "We used a GLP-1 and GLP-2 cellular knockout mouse model (Tg(GCG.DTR)) to demonstrate that the endogenous secretion of both hormones is essential for intestinal recovery and that substitution with both hormones is necessary to regain normal recovery after chemotherapy-induced mucositis." (PMID 29864142, 2018).
neuropathy (3 papers, 2020 to 2024). A disorder affecting the nervous system that manifests with pain, tingling, numbness, and/or muscle weakness. "Numerous studies have shown that neuropathy and aging are linked with glucose regulation and glucagon." (PMID 37691192, 2024).
overnutrition (3 papers, 2014 to 2024). An imbalanced nutritional status resulting from excessive intake of nutrients. "When IR occurs, the ability of insulin to inhibit hepatic glucose is decreased, hepatic gluconeogenesis is increased, may be caused by overnutrition, decreased portal vein insulin/glucagon ratios and/or impaired insulin signaling." (PMID 34093184, 2021). "Prolonged starvation, overnutrition, and glucagon all upregulated FGF21 expression, while insulin may inhibit FGF21 expression in the liver." (PMID 39296716, 2024).
pancreatic disease (3 papers, 2018 to 2025). "Moreover, most patients who undergo the glucagon stimulation test or BT-PABA test are generally suspected of having any pancreatic diseases based on symptoms or imaging findings." (PMID 30571730, 2018).
schizophrenia (3 papers, 2022 to 2026). A major psychotic disorder characterized by abnormalities in the perception or expression of reality. "For example, dysregulations of insulin, cortisol, glucagon, glucagon-like peptide 1, cholecystokinin, adiponectin, ghrelin, leptin, orexin, prolactin, and oxytocin have been observed during treatment with antipsychotics among persons with schizophrenia." (PMID 35806096, 2022).
thyroid (3 papers, 2021 to 2025). "In this study, the specific signaling pathways of LRRC were Wnt signaling pathway, gap junction, glucagon signaling pathway, axon guidance, thyroid hormone synthesis, morphine addiction, glycine, serine and threonine metabolism." (PMID 34642262, 2021).
alcoholic liver diseases (2 papers, 2025). A disorder caused by damage to the liver parenchyma due to alcohol consumption. "These pathways are implicated in a number of biological processes, including metabolic pathways, bile secretion, steroid biosynthesis, alcoholic liver disease, fatty acid metabolism, fatty acid degradation, the PPAR signaling pathway, the AMPK signaling pathway, and the glucagon signaling pathway." (PMID 40492727, 2025).
Alcoholism (2 papers, 2022 to 2023). "KEGG pathway enrichment analysis showed that DNA replication, Apelin signaling pathway, Glucagon signaling pathway, cGMP-PKG signaling pathway, PI3K-Akt signaling pathway, AMPK signaling pathway, Alcoholism, and Cocaine addiction might be involved in the pathological process of EMs and RPL." (PMID 35601407, 2022).
Autoimmunity (2 papers, 2009 to 2010). The occurrence of an immune reaction against the organism's own cells or tissues. "However, due to sequence similarities of EX with endogenous GLP-1 and glucagon (53% and 45% amino acid, respectively), formation of autoimmunity and immunoneutralisation of these related endogenous peptides by antiexenatide antibodies are potential hazards." (PMID 20582183, 2010). "Importantly, in rodent models of both autoimmunity and ß cell tumor development, we found increased DNA content only in β-cells and not in α-cells, based on glucagon staining and a comparable gating strategy." (PMID 19287497, 2009).
autonomic dysfunction (2 papers, 2021 to 2022). "Additionally, glucagon induces norepinephrine secretion, which might stimulate the release of GH via α-receptors; this mechanism could be of great interest in PWS because patients with PWS have underlying autonomic dysfunction." (PMID 32720093, 2021).
carbohydrate metabolism disorders (2 papers, 2022 to 2023). "Not only the frequency of carbohydrate metabolism disorders was analyzed, but also parameters determining pathogenetic phenomena related to glucose homeostasis - insulin sensitivity (HOMA-IR) and insulin secretion (OGTT, C-peptide - fasting and glucagon stimulated) were examined." (PMID 36589801, 2022).
cerebrovascular disease (2 papers, 2022 to 2026). "This association suggests a potential link between glucagon and cerebrovascular diseases in this population, warranting further investigation to explore its role." (PMID 41648993, 2026). "When contraindicated (patients with seizures and cardio/cerebrovascular disease), alternative tests such as the glucagon, the macimorelin, and the GHRH plus arginine/GH secretagogue tests can be used, which are well described elsewhere, although there is a lack of normative data at transition." (PMID 35262704, 2022).
cervical cancer (2 papers, 2016 to 2021). A primary or metastatic malignant neoplasm involving the cervix.